NEXN (nexilin F-actin binding protein)
Description:
Involved in regulating cell migration through association with the actin cytoskeleton. Has an essential role in the maintenance of Z line and sarcomere integrity.
Synonyms: nexilin; NELIN; CDM2M; CMH20
Tractability: Antibody: its Gene Ontology location is reachable by antibodies, with high confidence. PROTAC: ubiquitination databases record sites on it; its protein half-life has been measured.
Gene: Protein-coding gene on chromosome 1 (77,888,480 to 77,943,895, forward strand). Ensembl gene ENSG00000162614.
Subcellular location: Cytoplasm, cytoskeleton; Cell junction, adherens junction; Cytoplasm, myofibril, sarcomere, Z line
Subcellular location (Human Protein Atlas): Actin filaments; Plasma membrane
Gene Ontology:
Molecular function: actin filament binding; structural constituent of muscle; cell-cell adhesion mediator activity
Biological process: regulation of cell migration; regulation of cytoskeleton organization; axon guidance; dendrite self-avoidance; homophilic cell-cell adhesion
Cellular component: actin cytoskeleton; focal adhesion; axon; plasma membrane; Z disc; adherens junction; cytoskeleton
Genetic constraint (gnomAD): Loss-of-function variants: 56 observed, 79.72 expected, observed/expected ratio (o/e) 0.7, 90% interval 0.57 to 0.88. The upper end of that interval is the gene's LOEUF score, 0.88, which puts it in group 3 of 6, group 1 being the genes least tolerant of losing a copy. Missense variants: 686 observed, 720.18 expected, observed/expected ratio (o/e) 0.95, 90% interval 0.89 to 1.01. Synonymous variants: 229 observed, 227.69 expected, observed/expected ratio (o/e) 1.01, 90% interval 0.9 to 1.12.
Gene-disease validity (ClinGen):
ClinGen rates the evidence that NEXN causes each of these diseases.
dilated cardiomyopathy 1CC (autosomal dominant): Strong. Any familial isolated dilated cardiomyopathy in which the cause of the disease is a mutation in the NEXN gene.
hypertrophic cardiomyopathy (autosomal dominant): Limited. A condition in which the myocardium is hypertrophied without an obvious cause.
Homologues: Orthologues: chimpanzee NEXN (99% identical), macaque NEXN (98% identical), pig NEXN (94% identical), guinea pig NEXN (91% identical), mouse Nexn (89% identical), rat Nexn (87% identical), dog NEXN (85% identical), rabbit NEXN (85% identical), tropical clawed frog nexn (71% identical), zebrafish nexn (65% identical), Drosophila melanogaster Strn-Mlck (38% identical). Paralogues in human: MYLK (16% identical), DAPK3 (10% identical), DAPK1 (10% identical), DAPK2 (8% identical).